STAG2 (STAG2 cohesin complex component)
Description:
Component of cohesin complex, a complex required for the cohesion of sister chromatids after DNA replication. The cohesin complex apparently forms a large proteinaceous ring within which sister chromatids can be trapped. At anaphase, the complex is cleaved and dissociates from chromatin, allowing sister chromatids to segregate. The cohesin complex may also play a role in spindle pole assembly during mitosis.
Synonyms: SA2; SA-2; SCC3B; HPE13; MKMS; NEDXCF; bA517O1.1
Tractability: PROTAC: ubiquitination databases record sites on it; its protein half-life has been measured.
Gene: Protein-coding gene on chromosome X (123,960,212 to 124,422,664, forward strand). Ensembl gene ENSG00000101972.
Subcellular location: Nucleus; Chromosome; Chromosome, centromere
Subcellular location (Human Protein Atlas): Nucleoli; Nucleoli fibrillar center; Nucleoplasm
Pathways (Reactome):
Cell Cycle: Cohesin Loading onto Chromatin; Establishment of Sister Chromatid Cohesion; Resolution of Sister Chromatid Cohesion; Separation of Sister Chromatids
Metabolism of proteins: SUMOylation of DNA damage response and repair proteins
Reproduction: Meiotic synapsis
Signal Transduction: Estrogen-dependent gene expression
Gene Ontology:
Molecular function: protein binding; chromatin binding
Biological process: mitotic spindle assembly; sister chromatid cohesion; establishment of mitotic sister chromatid cohesion
Cellular component: chromatin; cohesin complex; fibrillar center; membrane; mitotic cohesin complex; mitotic spindle pole; nuclear matrix; nucleolus; nucleoplasm; chromosome; chromosome, centromeric region; cytosol; nucleus
Cancer hallmarks: cell replicative immortality (suppresses); genome instability and mutations (suppresses)
Homologues: Orthologues: chimpanzee STAG2 (100% identical), macaque STAG2 (99% identical), dog STAG2 (99% identical), rabbit STAG2 (99% identical), mouse Stag2 (99% identical), rat Stag2 (99% identical), pig STAG2 (96% identical), tropical clawed frog stag2 (91% identical), guinea pig STAG2 (87% identical), zebrafish stag2b (86% identical), zebrafish stag2a (76% identical), Caenorhabditis elegans scc-3 (30% identical), and 1 more. Paralogues in human: STAG1 (71% identical), STAG3 (48% identical).
Diseases named in the same sentence as STAG2 in open-access papers:
STAG2 is named in the same sentence as 103 diseases in open-access papers, as found by Europe PMC text mining. Sharing a sentence is not in itself a finding about the gene and the disease. The quoted sentences say what the papers report.
Ewing sarcoma (54 papers, 2013 to 2026). A small round cell tumor that lacks morphologic, immunohistochemical, and electron microscopic evidence of neuroectodermal differentiation. "Loss of STAG2 function in Ewing sarcoma cells alters chromatin architecture and, in combination with the disruption of PRC2, activates an oncogenic developmental program to promote migration and metastasis." (PMID 40983796, 2025). "Another insight from the study by Adane and colleagues is that a loss of STAG2 in Ewing sarcoma cell lines disrupts PRC2-mediated regulation in a subset of genomic regions." (PMID 39594644, 2024). "We have taken a different approach to further understand the consequences of STAG2 loss in Ewing sarcoma." (PMID 39487368, 2024). "It has been reported that loss of cohesin STAG2 alters transcription of Polycomb target genes in Ewing sarcoma cells." (PMID 39487368, 2024). "We investigated how the loss of STAG2 affects the levels of cohesin and its closest regulators in Ewing sarcoma cells, which in turn is likely to affect extrusion dynamics and thereby genome folding." (PMID 39487368, 2024). "We cannot exclude the possibility that loss of STAG2 affects Ewing sarcoma cells through mechanisms beyond gene expression regulation, including those related to genome instability." (PMID 39487368, 2024). "In the current study, we integrated gene expression data from patients and cellular models of Ewing sarcoma to identify a STAG2-dependent gene signature associated to worse prognosis." (PMID 39487368, 2024). "We next examined changes in gene expression unrelated to EWS::FLI1 in STAG2 deficient Ewing sarcoma cells." (PMID 39487368, 2024). "We conclude that STAG2 loss in Ewing sarcoma leads to transcriptional changes that extend beyond EWS::FLI1 target genes and that most likely contribute to adverse prognosis." (PMID 39487368, 2024). "A previous study showed reduced CTCF-anchored loop extrusion in STAG2 deficient Ewing sarcoma cells based on CTCF HiChIP data." (PMID 39487368, 2024). "Analysis of human cancer cell lines revealed frequent inactivating mutations of the STAG2 gene in glioblastoma, Ewing sarcoma, and melanoma primary tumors." (PMID 39594644, 2024). "STAG2 loss-of-function mutations promote metastasis in Ewing sarcoma, a pediatric cancer driven by the fusion transcription factor EWS::FLI1." (PMID 39487368, 2024). "Mechanistically, STAG2 loss of function favors invasiveness and metastasis of Ewing sarcoma cells by reducing cis-mediated EWSR1-FLI1 activity." (PMID 37723198, 2023). "STAG2 is among the few genes that are recurrently mutated in Ewing sarcoma, occurring in approximately 17% of patients and correlating with poorer prognosis." (PMID 36505823, 2022). "In Ewing sarcoma, loss of STAG2 expression can be secondary to STAG2 somatic mutations or loss of protein expression in the absence of a mutation." (PMID 36483025, 2022). "Nevertheless, it is intriguing that approximately 15% of Ewing sarcoma samples exhibited mutations in the STAG2 gene, making it one of the most commonly mutated genes in the disease." (PMID 31898537, 2020). "Recent studies have identified STAG2 mutation as one of the most common associated anomalies in Ewing sarcoma, occurring in approximately 15% of tumor samples." (PMID 31898537, 2020).
Ewing sarcoma (continued). "In summary, STAG2 mutations are a frequent characteristic of a few of the most common human cancers including glioblastoma, urothelial carcinoma, and Ewing sarcoma." (PMID 30975996, 2019). "STAG2 mutations have been described in various tumor types: bladder cancer, glioblastoma, melanoma, Ewing’s sarcoma and myeloid malignancies." (PMID 29088303, 2017). "Consistent with the results obtained in bladder cancer cells, STAG2 mutation status was also linked to STAG1 dependency in a panel of four Ewing sarcoma cell lines." (PMID 28691904, 2017). "Among solid human cancers, STAG2 mutational inactivation is most prevalent in urothelial bladder cancer and Ewing sarcoma." (PMID 28691904, 2017). "In our survey for genetic alterations, we discovered STAG2 mutations in 21.5% of Ewing sarcoma family tumor samples and 44.4% of EFT cell lines tested, the vast majority of which are inactivating mutations." (PMID 25010205, 2014). "Inactivating mutations in the cohesin complex component STAG2 have been reported in 5.9% of glioblastoma and at lower frequency in melanoma and Ewing's sarcoma and several other cancer types [COSMIC; cancer.sanger.ac.uk/cancergenome/projects/cosmic/]." (PMID 24270882, 2014). "In addition to this truncal driver, recurrent loss-of-function alterations in the cohesin subunit STAG2 occur in approximately 10 to 15% of Ewing sarcomas and are associated with adverse clinical outcomes." (PMID 41950086, 2026). "STAG2 knockout caused altered enhancer–promoter interactions in Ewing sarcoma cells." (PMID 39747661, 2025). "STAG2 deficient glioblastoma and Ewing sarcoma cells are more sensitive to DNA alkylating agents, DNA crosslinking agents, topoisomerase inhibitors, Poly (ADP-ribose) polymerase (PARP) inhibitors, and ataxia telangiectasia and Rad3-related protein (ATR) inhibitors." (PMID 40025053, 2025). "Furthermore, loss of function mutations in STAG2 occurs in 17% of Ewing sarcoma and is associated with a more aggressive tumour phenotype both in clinical studies and in murine xenograft models." (PMID 40983796, 2025). "Finally, STAG2 loss of function occurs recurrently in Ewing sarcoma and disrupts the repressive function of PRC2, leading to expression of developmental genes and induces a more aggressive and metastatic phenotype in murine models." (PMID 40983796, 2025). "STAG2 mutated Ewing sarcomas are associated with increased metastasis and poorer clinical outcomes." (PMID 40442778, 2025). "The core cohesion subunit STAG2 has been found to be frequently mutated in Ewing sarcoma." (PMID 39696530, 2024). "In summary, loss of STAG2 may contribute to the worse outcome of Ewing sarcoma patients through multiple mechanisms that remain to be elucidated in order to provide novel treatment options for cohesin-mutant patients." (PMID 39487368, 2024). "Similarly, many other cohesin-related gene mutations were detected in various tumors, such as mutations in SA2 and STAG2, which were found in bladder carcinoma, Ewing sarcoma, and melanoma." (PMID 35409298, 2022). "Interestingly, loss of STAG2 in Ewing sarcoma cells results in impaired loop extrusion and alters promoter-enhancer interactions which impedes the EWS::FLI1-dependent transcriptional program." (PMID 36505823, 2022). "On the contrary, loss of STAG2 promotes migratory and metastatic potential of Ewing sarcoma cells." (PMID 35371307, 2022). "STAG2 is expressed broadly in many different cell types, and yet STAG2 mutation is especially frequent in certain malignancies, including bladder cancer, uterine cancer, and Ewing sarcoma." (PMID 31898537, 2020). "However, the majority of STAG2 mutations in glioblastoma, urothelial carcinoma, and Ewing sarcoma are clonal events that likely arise early during tumor development." (PMID 30975996, 2019).
Ewing sarcoma (continued). "Recent genomic analyses of human cancer have identified that the cohesin genes, and STAG2 in particular, are frequent targets of mutational inactivation in a select subset of tumor types that include glioblastoma, urothelial carcinoma, Ewing sarcoma, and myeloid leukemia." (PMID 30975996, 2019). "We show that Ewing sarcoma patients whose tumors are affected by STAG2 loss may have a worse prognosis." (PMID 25010205, 2014). "STAG2 encodes a subunit of the cohesion complex that participates in mitotic chromatid separation and was recently found to show low expression and inactivating mutations in Ewing’s sarcoma, melanoma and glioblastoma." (PMID 24088605, 2013). "Furthermore, the association of STAG2-mutations with trisomy 8 is intriguing considering recent findings suggesting that RAD21 is the driver of chromosome 8 gain to mitigate replication stress in Ewing sarcoma, a disease characterized by frequent STAG2 mutations." (PMID 39033241, 2024). "However, the majority of urothelial carcinomas, Ewing sarcomas, and myeloid leukemias harboring STAG2 mutations are actually diploid or near-diploid tumors, suggesting that cohesin mutations in cancer likely promote tumorigenesis by mechanisms unrelated to chromosome segregation." (PMID 30975996, 2019). "Inactivating mutations of STAG2 have been found in glioblastoma, Ewing’s sarcoma and melanoma, possibly contributing to chromosome instability in these tumors and this led us to investigate whether they might also be responsible for the high aneuploidy rate seen in favorable NB tumors." (PMID 24088605, 2013). "This is contrary to the tumor suppressive role of STAG2 described in other cancer types such as Ewing sarcoma, acute myeloid leukemia, and pancreatic cancer." (PMID 40025053, 2025). "In addition to providing mechanistic understanding of the consequences of STAG2 loss for the transcriptome of Ewing sarcoma cells, our results identified a gene signature that could be further refined to select biomarkers useful for predicting disease progression and/or serve as therapeutic targets." (PMID 39487368, 2024). "Two complementary studies on Ewing sarcoma cell lines, where wild-type STAG2 was initially genetically ablated, revealed the disruption of a large number of enhancer–promoter interactions in STAG2 KO cells." (PMID 39594644, 2024). "Taken together, these results are in agreement with the formation of cohesin STAG2-dependent contacts in response to the presence of EWS::FLI1 in Ewing sarcoma cells, most prominently at long GGAA repeats." (PMID 39487368, 2024). "As was found in previous studies, STAG2 mutations correlated with sensitivity to PARP inhibition with talazoparib, particularly in Ewing’s sarcoma." (PMID 37020198, 2023). "STAG2 is frequently inactivated in cancer, particularly glioblastoma, urothelial carcinoma, Ewing sarcoma and myeloid leukemia." (PMID 38201285, 2023). "A similar increased sensitivity to PARP inhibition was observed in STAG2-depleted glioblastoma, Ewing sarcoma, hTERT-positive retinal pigmented epithelial cells and in certain STAG2 mutant leukemia cells." (PMID 34202641, 2021). "STAG2 knockout in Ewing sarcoma cell lines was found to downregulate EWSR1-FLI1-anchored chromatin interactions and enhance the migratory potential of these cells." (PMID 34202641, 2021).
Ewing sarcoma (continued). "That was the case for Neurofibromatosis Type II (NF2) and STAG2 that was shown to predispose for MISME (“Multiple Inherited Schwannomas, Meningiomas, and Ependymomas”) Syndrome and Ewing sarcoma respectively." (PMID 31105870, 2019). "Finally,we identified additional genomic features from ctDNA including identification of apreviously undescribed EWSR1 fusion, STAG2 loss in Ewing sarcoma, and 8q gain in osteosarcoma.Our results demonstrate that these two ctDNA assays may yield additional informationabout tumour biology." (PMID 30131550, 2018). "Tissue microarrays (TMA) from an independent cohort of genetically confirmed Ewing sarcoma cases were evaluated for STAG2 expression by IHC." (PMID 25010205, 2014). "STAG2 occupies enhancer and PRC2-marked regulatory regions, its loss leads to reprogramming of the oncogenic and neurodevelopmental transcriptomes and causes increased metastatic potential of Ewing sarcoma cells in mouse models." (PMID 39696530, 2024). "Analysis of enhancer-promoter contacts in Ewing sarcoma cells with and without cohesin STAG2 detects loss and gain of contacts that likely contribute to transcriptome changes identified in these cells and in STAG2 mutant tumors." (PMID 39487368, 2024). "STAG1 inactivation inhibits the proliferation of STAG2 mutations but not in Ewing’s sarcoma and bladder cancer." (PMID 39390002, 2024). "To understand how the loss of cohesin STAG2 affects Ewing sarcoma patients, we thoroughly compared the transcriptomes of patients and cell lines with and without STAG2." (PMID 39487368, 2024). "Both STAG2 mutations and the expression of EWS-FLI1 fusion are frequently encountered in Ewing’s sarcoma and are likely an explanation to why this tumor type demonstrates an overall greater sensitivity to PARP inhibition compared to other pediatric tumor types." (PMID 37020198, 2023). "STAG2 mutant glioblastoma, Ewing sarcoma and hTERT-positive retinal pigmented epithelial cells are sensitive to several DNA alkylating agents (cyclophosphamide, gemcitabine and temozolomide), ATR kinase inhibitors (VX-970, AZD6738), topoisomerase poisons (doxorubicin, etoposide and topotecan)." (PMID 34202641, 2021). "STAG2, a gene commonly altered in Ewing sarcoma and associated with a poor prognosis, was not altered in a single subject with EWSR1-NFATc2 positive sarcoma." (PMID 34021224, 2021). "STAG1 inactivation inhibits the proliferation of STAG2 mutated but not wild-type bladder cancer and Ewing sarcoma cell lines." (PMID 28691904, 2017). "For example, it has been shown that, STAG2-deficient glioblastoma cells, although not STAG2-deficient Ewing sarcoma cells, are more responsive than STAG2 proficient cells to treatment with PARP inhibitors." (PMID 28430577, 2017). "The development of in vivo models and analysis of the immune environment in patients with and without STAG2 mutations will be important future directions for exploring the contribution of immune evasion to aggressive Ewing sarcoma and its implications for immunotherapy." (PMID 39487368, 2024). "Whether STAG2 is prognostic among patients with localised Ewing sarcoma treated with standard of care vincristine/doxorubicin/cyclophosphamide alternating with ifosfamide/etoposide (VDC/IE) remains a central question in future efforts to test-risk-stratified therapy in this population." (PMID 36221002, 2022).